EIF4EBP2 (eukaryotic translation initiation factor 4E binding protein 2)
Description:
Repressor of translation initiation involved in synaptic plasticity, learning and memory formation. Regulates EIF4E activity by preventing its assembly into the eIF4F complex: hypophosphorylated form of EIF4EBP2 competes with EIF4G1/EIF4G3 and strongly binds to EIF4E, leading to repress translation. In contrast, hyperphosphorylated form dissociates from EIF4E, allowing interaction between EIF4G1/EIF4G3 and EIF4E, leading to initiation of translation. EIF4EBP2 is enriched in brain and acts as a regulator of synapse activity and neuronal stem cell renewal via its ability to repress translation initiation (By similarity). Mediates the regulation of protein translation by hormones, growth factors and other stimuli that signal through the MAP kinase and mTORC1 pathways (By similarity).
Synonyms: 4EBP2; PHASII
Tractability: Small molecule: a structure with a bound ligand is known. PROTAC: its protein half-life has been measured.
Gene: Protein-coding gene on chromosome 10 (70,404,144 to 70,428,618, forward strand). Ensembl gene ENSG00000148730.
Subcellular location: Cytoplasm; Nucleus
Subcellular location (Human Protein Atlas): Mitochondria; Nucleoplasm
Gene Ontology:
Molecular function: protein binding; translation repressor activity; eukaryotic initiation factor 4E binding
Biological process: negative regulation of translational initiation; memory; modulation of chemical synaptic transmission; regulation of synaptic plasticity; social behavior; TOR signaling; translation
Cellular component: cytoplasm; neuronal ribonucleoprotein granule; nucleus; postsynapse
Genetic constraint (gnomAD): Loss-of-function variants: 4 observed, 5.41 expected, observed/expected ratio (o/e) 0.74, 90% interval 0.36 to 1.61. That is too few expected variants to judge how well the gene tolerates losing a copy. Missense variants: 143 observed, 107.12 expected, observed/expected ratio (o/e) 1.34, 90% interval 1.16 to 1.53. Synonymous variants: 57 observed, 44.15 expected, observed/expected ratio (o/e) 1.29, 90% interval 1.04 to 1.61.
Homologues: Orthologues: chimpanzee EIF4EBP2 (100% identical), macaque EIF4EBP2 (100% identical), dog EIF4EBP2 (99% identical), rabbit EIF4EBP2 (99% identical), mouse Eif4ebp2 (95% identical), pig EIF4EBP2 (92% identical), rat Eif4ebp2 (90% identical), guinea pig EIF4EBP2 (89% identical), tropical clawed frog eif4ebp2 (77% identical), zebrafish eif4ebp2 (70% identical), Drosophila melanogaster Thor (38% identical), zebrafish gra (24% identical). Paralogues in human: EIF4EBP1 (58% identical), EIF4EBP3 (51% identical).
Diseases named in the same sentence as EIF4EBP2 in open-access papers:
EIF4EBP2 is named in the same sentence as 36 diseases in open-access papers, as found by Europe PMC text mining. Sharing a sentence is not in itself a finding about the gene and the disease. The quoted sentences say what the papers report.
autism (4 papers, 2013 to 2022). Persistent deficits in social interaction and communication and interaction as well as a markedly restricted repertoire of activity and interest as well as repetitive patterns of behavior. "In the brain, eIF4EBP2 appears to act downstream of TORC1 signaling to control the translation of specific mRNAs involved in synaptogenesis and linked to autism." (PMID 24143132, 2013). "Mutations in the eIF4E promoter are present in some individuals with autism, and eIF4EBP2 knockout and eIF4E-overexpressing mice exhibit autism-like phenotypes, strengthening the hypothesis that disruptions in mTOR-dependent protein synthesis contribute to autism pathology." (PMID 29691724, 2018).
breast carcinoma (4 papers, 2011 to 2024). "A negative regulator of translation, eIF4EBP2, has been shown to be altered in breast cancer cells upon inhibition of proteasome." (PMID 21811619, 2011). "Gene expression analysis showed that the expression level of Eif4ebp2 was higher in the radiosensitive breast cancer cells when compared to the radioresistant cells, suggesting that Eif4ebp2 might be a biomarker of radiotherapy reaction in breast cancer." (PMID 39451223, 2024).
memory impairment (3 papers, 2023 to 2026). "Therefore, it can be inferred that EIF4EBP2 is related to the inferior temporal gyrus, which can cause memory impairment, and RTN4 is related to the middle temporal gyrus, which can cause alexia." (PMID 37238598, 2023).
diabetes (2 papers, 2015 to 2020). "4EBP1 was also positively associated with genes coupled to diabetes pathways, genes regulated by the transcription factors E2F, USF and SP1, the oncogenes HRAS and HOXB13 and several genes involved in negative regulation of translational initiation (EIF4EBP2, EIF2B3, EIF2C2)." (PMID 26698305, 2015). "Our data indicated that the risk of diabetes varied with mTOR downstream target EIF-4E and EIF-4A, but not with RP-S6K or EIF4EBP2." (PMID 32978410, 2020).
Dyskinesia (1 paper, 2023). A movement disorder which consists of effects including diminished voluntary movements and the presence of involuntary movements. "Martín-Flores, N showed the significant association of SNP rs1043098 in the EIF4EBP2 gene with the onset of dyskinesia induced by L-DOPA administration." (PMID 36952494, 2023).
multiple sclerosis (1 paper, 2023). A progressive autoimmune disorder affecting the central nervous system resulting in demyelination. "In multiple sclerosis patients, EIF4EBP2 expression was downregulated compared to those in healthy controls." (PMID 36952494, 2023).
type 2 diabetes (1 paper, 2020). "In this study, we investigated whether the risk of type 2 diabetes varied with EIF4EBP2, EIF-4E, EIF-4G, EIF-4A, and RP-S6K levels using the Mendelian Randomization approach." (PMID 32978410, 2020). "We estimated the causal role of EIF-4F complex, EIF4EBP, and S6K in the circulation on type 2 diabetes, based on independent single nucleotide polymorphisms strongly associated (p = 5 × 10–6) with EIF-4E (16 SNPs), EIF-4A (11 SNPs), EIF-4G (6 SNPs), EIF4EBP2 (12 SNPs), and RP-S6K (16 SNPs)." (PMID 32978410, 2020).
tumor (8 papers, 2009 to 2025). "A total of 127 genes were upregulated upon JQ1 treatment and included those with a role in translational repression (EIF4EBP2, PAIP2B), induction of apoptosis (PPP1R13B) and tumour suppression (glucocorticosteroid (GC)-responsive gene FKBP51)." (PMID 23872705, 2013).
EIF4EBP2 also shares sentences with these, for which no sentence is quoted: cancer (5 papers); Insulin resistance (5); ischemia (4); Cerebral ischemia (3); epilepsy (2); infection (2); neurodegenerative disease (2); neurodevelopmental disorder (2); Obesity (2); pancreatic cancer (2); Parkinson’s (2); transient cerebral ischemia (2); Alzheimer disease (1); astrocytomas (1); atopic dermatitis (1); autism spectrum disorder (1); brain diseases (1); breast tumours (1); Ewing sarcoma (1); glioblastoma (1); glioma (1); hyperglycaemia (1); lymphoma (1); metabolic disorder (1); neuroblastoma (1); oligodendroglioma (1); polycystic kidney (1); viral infection (1).